ACE (angiotensin I converting enzyme)
Diseases named in the same sentence as ACE in open-access papers (continued):
Sharing a sentence is not in itself a finding about the gene and the disease.
atrial fibrillation (123 papers, 2005 to 2025). A disorder characterized by an electrocardiographic finding of a supraventricular arrhythmia characterized by the replacement of consistent P waves by rapid oscillations or fibrillatory waves that vary in size, shape and timing and are accompanied by an irregular ventricular response. "Ueberhamet al. found that ACE DD genotype was a risk factor forthe recurrence of atrial fibrillation using multivariate logistic regressionanalysis in a study of 238 patients with atrial fibrillation." (PMID 39076272, 2023). "Chronic persistent and paroxysmal atrial fibrillation are associated with increased ACE activity, along with increased activated ERK-1/ERK-2 and the ERK activating kinases (MEK 1/MEK2) in the interstitial cells associated with marked atrial fibrosis." (PMID 32217149, 2020). "ACE DD gene polymorphism was independently associated with atrial fibrillation recurrence." (PMID 39076272, 2023). "Significant differences in the local conformations and kinetic properties of heart and lung ACEs demonstrate tissue specificity of ACE and provide a structural base for the development of mAbs able to distinguish heart and lung ACEs as a potential blood test for predicting atrial fibrillation risk." (PMID 28771512, 2017). "Angiotensin-converting enzyme (ACE) inhibitors offer protection against myocardial fibrosis, prevent cardiac remodeling, and reduce the risk of atrial fibrillation." (PMID 40299454, 2025). "Among patients who experienced one or more CVAEs, direct oral anticoagulants were initiated in three patients for atrial fibrillation, and an ACE inhibitor was initiated in one patient." (PMID 41007747, 2025). "In the group without CVAEs, a direct oral anticoagulant was initiated in one patient for an indication other than atrial fibrillation, and the ACE inhibitor dosage was reduced in one patient." (PMID 41007747, 2025). "Patients with septal LGE were more likely to be women (P = 0.029), to present with breathlessness or for familial cardiomyopathy screening (P < 0.0001), to have atrial fibrillation (P = 0.028), and to be prescribed an ACE inhibitor (P = 0.027)." (PMID 34274268, 2021). "In patients with HTN and LVH, ACE inhibitors or ARBs are effective for primary prevention of atrial fibrillation." (PMID 26893917, 2015). "The atrial fibrillation resolved spontaneously, and treatment with an angiotensin converting enzyme (ACE)-inhibitor was started." (PMID 18163912, 2007). "Therefore, we investigated the association of tSNPs in RAS gene (ACE gene rs8066114, AGT gene rs7539020, rs3789678, rs2478544, rs11568023, rs2478523, rs4762, rs699 and CYP11B2 rs3802230, rs3097) and atrial fibrillation in a Chinese Han sample." (PMID 25723521, 2015). "However, the benefits of ACE inhibitors are negligible in patients with chronic atrial fibrillation or known atherosclerosis." (PMID 26893917, 2015). "The aim of this study was to investigate the potential associations of angiotensin-converting enzyme (ACE) gene insertion/ deletion (I/D) and aldosterone synthase (CYP11B2) gene −344T/C polymorphisms with the risk and recurrence of lone atrial fibrillation (AF)." (PMID 23170137, 2012). "ACE: angiotensin converting enzyme; AF: atrial fibrillation; INR: international normalized ratio; PCI: percutaneous coronary intervention; SD: standard deviation." (PMID 26465747, 2015). "The investigators concluded that atrial fibrillation is an important complication of CABG, and they suggested preventing it by administering β-blockers and ACE inhibitors." (PMID 19232084, 2009). "The strongest predictors of early VAs after LVAD implantation are a pre-implant history of VAs, pre-implant atrial fibrillation, HF lasting over 12 months, and the absence of therapy with ACE inhibitors and beta-blockers." (PMID 41010807, 2025).
atrial fibrillation (continued). "In contrast to some studies that suggested ACE inhibitors as effective non-antiarrhytmic drugs in preventing atrial fibrillation, our study failed to prove their influence on atrial fibrillation." (PMID 21328722, 2011). "Similarly, history of VAs, lack of treatment with ACE inhibitors, HF duration exceeding 12 months, early VAs after implantation, history of atrial fibrillation, and non–ischemic cardiomyopathy were identified in the VT-LVAD score as predictors of late VAs." (PMID 41010807, 2025). "Furthermore, nonconsenting patients suffered more from atrial fibrillation, more frequently had a pacemaker, and were more likely to be on ACE inhibitors (supplementary S2)." (PMID 34145796, 2021). "Therapies targeting this pathway including angiotensin-converting enzyme (ACE) inhibitors and angiotensin-II receptor blockers (ARB) have been hypothesized to be beneficial in preventing atrial fibrillation occurrence and are currently the focus of numerous studies." (PMID 30534081, 2018).
endothelial dysfunction (123 papers, 2005 to 2026). In vascular diseases, endothelial dysfunction is a systemic pathological state of the endothelium (the inner lining of blood vessels) and can be broadly defined as an imbalance between vasodilating and vasoconstricting substances produced by (or acting on) the endothelium. "A study on cardiomyopathic Syrian hamsters, an animal model with a genetic predisposition to endothelial dysfunction attributed to its reduced expression of eNOS, reported an increase in eNOS expression upon chronic treatment with an ACE inhibitor." (PMID 39057713, 2024). "In these populations, endothelial dysfunction is a hallmark of the disease and most treatments that improve vascular outcomes, such as ACE inhibitors or statins, also improve endothelial dysfunction." (PMID 39606217, 2024). "There appears to be selective targeting of the tissular ACE population linked to endothelial dysfunction by the lipophilic enalapril." (PMID 38137544, 2023). "The results of this study indicate that plasma ACE level has an important role in the risk of ASCVD and cardiovascular mortality, in which plasma ACE will affect inflammation, oxidative stress, endothelial dysfunction, and vascular and myocardial remodeling." (PMID 35885904, 2022). "Previous studies have shown that ACE DD had close association with a high incidence of cardiovascular disease or endothelial dysfunction." (PMID 33041838, 2020). "Previous data have suggested that nicotine increases ACE expression and the D allele smokers have been found to be associated with endothelial dysfunction." (PMID 25984491, 2014). "The authors hypothesized that this increase might be associated with reduced ACE activity in the context of endothelial dysfunction, which prevents the conversion of Ang I into Ang II." (PMID 40126750, 2025). "Some of these hydrolysates also exerted antioxidant effects, improved HTN-associated endothelial dysfunction, and reduced ACE activity in different in vivo hypertensive models, which may contribute to their antihypertensive activity." (PMID 36678328, 2023). "Whether 6β-OHT increases the aortic expression of AT1 receptor and ACE that contributes to the effect of Ang II to increase vascular reactivity and cause endothelial dysfunction, hypertrophy, aortic fibrosis, and ROS production remains to be determined." (PMID 31948482, 2020). "In addition, ACE gene polymorphism has been shown to be closely associated with endothelial dysfunction." (PMID 33041838, 2020). "Indeed, smoking and the D allele increase ACE expression, impair protective antioxidant mechanisms, causing endothelial dysfunction by accelerating superoxide anion formation and degradation of nitric oxide, leading to the onset of STEMI19–21." (PMID 31873176, 2019). "In terms of vascular abnormalities, angiotensin-converting enzyme (ACE) gene deletion polymorphisms might lead to endothelial dysfunction and an increased susceptibility to migraine attacks." (PMID 29357368, 2018). "The angiotensin-converting-enzyme system plays an important role in the pathogenesis and progression of endothelial dysfunction, and ACE inhibitors were shown to be useful for reducing the risk of cardiovascular events in clinical and subclinical peripheral artery disease." (PMID 23509696, 2013). "RAAS involvement in OxSt amplification is proven by the antioxidant action of angiotensin-converting enzyme inhibitors (ACE inhibitors), adding to their preventive effects on endothelial dysfunction." (PMID 40722862, 2025). "In a Cyp4a12 transgenic mouse model of 20-HETE-dependent hypertension, Gpr75 knockdown significantly reduced doxycycline-induced blood pressure elevation, decreased ACE expression, and improved endothelial dysfunction." (PMID 40362321, 2025). "Certain therapies such as statins, ACE-Is, ARNI, SGLT2-is, and GLP-1RAs demonstrated a potential beneficial effect on endothelial dysfunction, reversing this pathogenic substrate and improving CMD and ACM manifestations." (PMID 36836800, 2023).
endothelial dysfunction (continued). "An increase in levels of endogenous antioxidant compounds, a reduction in ACE activity, and an improvement of HTN-associated endothelial dysfunction were the mechanisms underlying their effects." (PMID 36678328, 2023). "Another reported genetic variant in CTEPH is angiotensin-converting enzyme (ACE), which plays a key role in the renin–angiotensin system and can cause endothelial dysfunction, inflammation, and vascular remodeling." (PMID 38255153, 2023). "miR-27a increases ACE expression and thus leads to HTN by activating the NFκB pathway causing cardiovascular inflammation and remodeling, ROS generation, and endothelial dysfunction." (PMID 35071600, 2022). "GPR75 interaction with GPCR kinase-1 leads to c-Src-mediated activation of EGFR, upregulation of angiotensin-converting enzyme (ACE) and endothelial dysfunction." (PMID 35203616, 2022). "Tripeptide LSW, initially identified as a potent ACE inhibitory peptide from soybean protein, was recently reported to exert a protective effect against angiotensin II-induced endothelial dysfunction via extracellular vesicles (EVs)." (PMID 36296612, 2022). "Vasoconstriction shows its pro-hypertensive effect through increasing myogenic tone, tubuloglomerular feedback, smooth muscle cell migration and proliferation (vascular remodeling), endothelial dysfunction, ACE expression and inflammation." (PMID 35203616, 2022). "The angiotensin receptor blocker (ARBs) and angiotensin-converting enzyme (ACE) inhibitors can improve endothelial dysfunction and vascular inflammation." (PMID 33670754, 2021). "The results obtained in the present study have highlighted that endothelial dysfunction impacts bone mass through genetic participation of eNOS, ACE and VEGFA genes." (PMID 33499313, 2021). "In contrast, angiotensin-converting enzyme (ACE) inhibitors and angiotensin II (Ang II) receptor type I blockers have been used for a long time to prevent endothelial dysfunction in T2DM patients." (PMID 33322185, 2020). "The current study findings showed that endothelial dysfunction and aortic hypertrophy were the consequence of decreased eNOS expression and plasma NOx, as well as increased serum ACE activity and ang II in LHR." (PMID 33007813, 2020). "Many studies have investigated the relationship between angiotensin-converting enzyme (ACE) D/I polymorphism and cardiovascular disease or endothelial dysfunction; however, hardly any of these studies has taken aging or menopause into consideration." (PMID 33041838, 2020). "These abnormalities include increased vascular ACE activity, ROS-mediated endothelial dysfunction in the coronary circulation, and impaired acetylcholine-induced relaxation in aortic rings." (PMID 27420103, 2016). "It has been demonstrated that treatment with ACE-Is results in regression of small artery remodeling and endothelial dysfunction present in hypertensive patients." (PMID 21085521, 2010). "Endothelial dysfunction by PM in cardiac tissue can be further inferred from induction of ET-1 and activation of the ACE system in cardiac tissue following instillation of high PM2.5-AB." (PMID 20920269, 2010). "Several hypotheses have been proposed, ranging from endothelial dysfunction to the presence of circulating ACE inhibitors." (PMID 40126750, 2025). "In continuation of the prothrombotic cascade likely promoted by hyperhomocysteinemia and endothelial dysfunction related to the MTHFR C677T variant, the ACE I/D polymorphism may have added a further mechanistic layer to the patient’s vascular vulnerability." (PMID 40981125, 2025). "Based on this finding, the authors hypothesized that the activity of the angiotensin converting enzyme (ACE) was reduced in patients with septic shock and/or endothelial dysfunction." (PMID 38515121, 2024).
endothelial dysfunction (continued). "Hyper-activation of ACE/Ang II/AT1 axis or dysregulation of ACE-2/Angiotensin 1–7 (Ang 1–7) MasR axis potentially aggravates endothelial dysfunction, fibrosis, oxidative stress, monocyte/macrophage cell infiltration to perivascular tissue, in the kidney and heart, leading to blood pressure rise." (PMID 37854465, 2023). "Thus, ACE inhibitors or angiotensin II receptor blockers (ARBs) can prevent endothelial dysfunction induced by free fatty acids." (PMID 35163232, 2022). "For instance, statins have, among others, pleiotropic anti-inflammatory effects and may attenuate endothelial dysfunction via upregulation of ACE." (PMID 35054468, 2022). "In the D/D genotype, endothelial dysfunction occurs due to increased serum ACE concentration, which may catalyze various ischemic events." (PMID 36505135, 2022). "Omapatrilat and lisinopril+sacubitril had similar effects on vascular contraction, endothelial dysfunction, and arterial remodeling in hypertensive mice, and both treatments reduced tissue Ang II levels, again demonstrating the efficacy of combination ACE and NEP inhibition." (PMID 34304582, 2021). "Moreover, we discuss the potential therapeutic effect of angiotensin receptor blockers (ARBs), ACE inhibitors (ACE-I), and related substances such as vitamin D and bradykinin for preventing endothelial dysfunction." (PMID 33801921, 2021). "Several systematic reviews and meta-analyses revealed that ACE inhibitors, in addition to angiotensin receptor blockers (ARBs), have been shown to improve endothelial dysfunction by flow-mediated vasodilatation (FMD), a widely-used method for evaluate endothelial function." (PMID 33801921, 2021). "Similarly, in another study of male patients with chronic obstructive pulmonary disease, a significantly lower incidence of endothelial dysfunction (FMD < 10%) was observed in patients of ACE DI/II than in ACE DD." (PMID 33041838, 2020). "In addition, malvidin, Mv-3-glc, Mv-3-gal, and BAE still also prevent endothelial-dysfunction-induced vasoconstriction by decreasing the expression levels of ACE, XO-1, and LDL in human endothelial cells." (PMID 32106617, 2020). "Specific classes of phenolic compounds or their metabolites have been reported to improve endothelial dysfunction through their antioxidant attitude, but also directly acting over NO metabolism or reducing vasoconstriction by acting on ACE and angiotensin II receptor activity." (PMID 31159186, 2019). "In this sense, several drugs, including ACE inhibitors and statins, have demonstrated antioxidant and anti-inflammatory actions and a protective effect against endothelial dysfunction through different mechanisms, and their combination achieves additional beneficial effects than monotherapies." (PMID 29304136, 2018). "Renin-angiotensin system may contribute to the endothelial dysfunction; angiotensin-converting enzyme (ACE), which converts Ang I to Ang II, is mainly expressed in ECs." (PMID 23935243, 2013). "Candidate genes reported as associated with SICH were involved in the pathways of the vessel wall integrity (ACE, APOE, neprilysin, endoglin, TGF-β1), endothelial dysfunction (ACE), inflammation markers (IL-6, TNF), and hemostasis (APOE, CD-14, Factor VII and XIII, VKORC1)." (PMID 20534169, 2010). "Researchers have demonstrated that ACE inhibitors could improve endothelial dysfunction by enhancing the release of nitric oxide from endothelial cells to induce vasodilation and the capability of inhibiting ACE activity with an HPD may explain the improvement in FMD." (PMID 39013196, 2025). "Besides, ACE produces the potent vasoconstrictor angiotensin II, which is known to be a key mediator in the development of pulmonary hypertension, vascular remodeling and endothelial dysfunction." (PMID 33619211, 2021).
endothelial dysfunction (continued). "Nevertheless, ACE inhibitors have proven to be potent and effective agents in SHRs for the reduction in blood pressure and regression of several abnormalities, including cardiac and renal hypertrophy and endothelial dysfunction, that are developed in this model of genetic hypertension." (PMID 34711215, 2021). "Moreover, reductions in NO at the vascular level in young SCH may be central to triggering transient vascular ACE activation and to perpetuating endothelial dysfunction by promoting oxidative stress." (PMID 27420103, 2016). "Serum ACE rose significantly (p=0.032), aligning with the concept that sustained HTN activates RAS, enhancing Ang II production and exacerbating endothelial dysfunction." (PMID 41189776, 2025). "Consequently, the agonist-stimulated B2 bradykinin receptor could become anti-atherogenic upon treatment with an ACE inhibitor, which prevents endothelial dysfunction triggered by oxidized low-density lipoproteins in a B2 bradykinin receptor stimulation-dependent manner." (PMID 30847343, 2019). "This modification enhanced ACE reactivity toward Ang II and consequently led to NADPH oxidase-superoxide-dependent endothelial dysfunction." (PMID 28443021, 2017). "The fact that both ACE inhibitors and AT1R blockers prevented the endothelial dysfunction in diabetic animals and humans indicates a determinant role of the angiotensin system." (PMID 23755196, 2013). "Plasma levels of renin, angiotensin I (Ang I), angiotensin II (Ang II), angiotensin 1-7 (Ang 1-7), the Ang II/Ang I ratio (as a surrogate of ACE activity), and asymmetric dimethylarginine (ADMA)-a marker of endothelial dysfunction -were measured at baseline (D0) and day 3 (D3)." (PMID 41663785, 2026). "The findings of ACE/ACE2 imbalance, dysregulation of immune responses, endothelial dysfunction, and angiogenesis impairment in the elderly might explain the more severe conditions and cardiovascular involved in the old patients of COVID-19 infection." (PMID 35600485, 2022). "Indeed, angiotensin-converting enzyme (ACE) inhibitors and angiotensin II (Ang II) receptor type I blockers prevented endothelial dysfunction in diabetic animals and humans." (PMID 23755196, 2013). "Interestingly, a mouse model lacking GRP75 prevented blood pressure elevation, ACE expression, endothelial dysfunction, and smooth muscle contractility induced by 20-HETE." (PMID 36144261, 2022). "Finally, we tried to determine whether IRE1α/XBP1s/HIF1α pathway activation, which mediates augmented ACE/ANGII/AT1R axis components, also contributes to regulating ANGII-dependent endothelial dysfunction under PM2.5 exposure." (PMID 29044123, 2017).